IL13RA2 (interleukin 13 receptor subunit alpha 2)
Diseases named in the same sentence as IL13RA2 in open-access papers (continued):
Sharing a sentence is not in itself a finding about the gene and the disease.
cancer (continued). "It opens venues for the exploration of scFv47-based viral, cellular, protein, and nanoparticle therapeutics for the treatment of various IL13Rα2-expressing human malignancies." (PMID 26656559, 2015). "Collectively, this evidence suggests that targeting IL13Rα2 is likely to suppress metastasis, at least in part, by reducing cancer cell migration and inhibiting extravasation to the lungs." (PMID 26208975, 2015). "IL13 receptor α2 (IL13Rα2) is a high-affinity IL13 receptor overexpressed in a variety of human cancer types." (PMID 26682245, 2015). "Similar IL-13Rα2-dependent effects have been demonstrated in other cancer models, including ovarian carcinoma, colorectal cancer, head and neck squamous cell carcinoma, and malignant glioma." (PMID 24672527, 2014). "Another remarkable finding has been the role of IL-13Rα2 in models of cancer development, indicating signaling functions far beyond the previously suggested role of a decoy receptor." (PMID 24672527, 2014). "Since IL-13Rα2 is over-expressed in about 33% of human HNSCCs, we decided to examine the tumors of these mice for this unique cancer marker." (PMID 23421960, 2013). "Immunotoxin therapy by IL-13-PE will essentially target cancer cells that upregulate IL-13Rα2 and will therefore select against its expression." (PMID 23421960, 2013). "We found that a recombinant IL-13-PE immunotoxin targeting IL-13Rα2 has remarkable anti-cancer activity against these tumors." (PMID 23421960, 2013). "Primary cultures were derived from the tumors of the Tgfbr1/Pten 2cKO mice to determine if the upregulated expression of IL-13Rα2 by the cancer cells would make them sensitive to the IL-13-PE cytotoxicity." (PMID 23421960, 2013). "The isolated primary cancer cells from the Tgfbr1/Pten 2cKO mice retain higher expression of IL-13Rα2 as compared to other tissues, including the spleen, lung, kidney, liver, and skin." (PMID 23421960, 2013). "Interleukin-13 Receptor α2 (IL-13Rα2) is a high affinity receptor for the Th2 derived cytokine IL-13 and a known cancer testis antigen." (PMID 21477288, 2011). "HDAC inhibitors dramatically sensitized cancer cells to immunotoxin in the cytotoxicity assay in vitro and increased IL-13Rα2 in the tumors subcutaneously implanted in the immunodeficient animals but not in normal mice tissues." (PMID 21477288, 2011). "Since IL-13Rα2 is heterogeneously overexpressed in a variety of human cancers, it would be highly desirable to uniformly upregulate IL-13Rα2 expression in tumors for optimal targeting." (PMID 21477288, 2011). "IL-13Rα2 is over expressed in a variety of human cancers including malignant glioma, head and neck cancer, Kaposi's sarcoma, renal cell carcinoma, and ovarian carcinoma." (PMID 21477288, 2011). "IL-13Rα2 signaling can promote cancer survival, proliferation, invasion, and metastasis." (PMID 40114916, 2025). "In addition to its role as a cytokine receptor, IL-13Rα2 has also been characterized as a cancer-testis antigen." (PMID 40855097, 2025). "However, the relationship between IL13RA2 and patient prognosis is variable, and the biological function of this receptor in cancer remains controversial." (PMID 40663259, 2025). "Recently, IL13RA2 expression has been examined in plentiful cancers." (PMID 39220137, 2024). "TAMs‐secreted chitinase 3‐like protein 1 (CHI3L1), which is a glycoprotein highly expressed on cancer cells, promotes gastric and breast cancer metastasis by interacting and activating the interleukin‐13 receptor α2 chain (IL‐13Rα2) molecules present on cancer cells." (PMID 38703051, 2024). "Other studies have reported targeting of IL‐13Rα2 positive cancer by CAR‐T cells." (PMID 38685487, 2024). "However, TSA and 5-aza-dC significantly increased the sensitivity of the low-IL-13Rα2-expressing cancer cell line (LNCaP) to Pep-1-Phor21." (PMID 36830725, 2023). "It is currently unknown how effective this lytic peptide will be against other cancers overexpressing IL-13Rα2." (PMID 36830725, 2023).
cancer (continued). "We next determined whether the sensitivity of the cancer cells to the hybrid lytic peptide could be altered by upregulating IL-13Rα2 expression by treatment with epigenetic inhibitors." (PMID 36830725, 2023). "Since SHN3 participates in the regulation of AP-1 or NF-κB transcriptional activity in IL13Rα2-positive cancer cells, a coordinated action of these transcription factors might explain the regulation of MMP9 expression." (PMID 37963919, 2023). "Because IL13Rα2 is considered to be a decoy receptor, it might be secreted from cancer cells into serum." (PMID 36806727, 2023). "Accordingly, it has been argued that IL13Rα2 is a form of cancer-testis antigen." (PMID 36829563, 2023). "Moreover, SHN3 expression strongly correlated with IL13Rα2 and MMP9-associated poor prognosis in different cancers." (PMID 37963919, 2023). "In recent years, IL13RA2 has also been reported as a marker for several cancer cells." (PMID 37445678, 2023). "The suppressive effect of K284 on the CHI3L1/IL‐13Rα2 interaction could inhibit cancer cell growth‐related downstream signals." (PMID 34758182, 2022). "Application of these CARs could expand the therapeutic window for systemic administration of IL13Rα2-targeted therapy for a variety of cancers." (PMID 35939683, 2022). "CHI3L1 specifically binds to IL‐13Rα2 in cancer cells, thus promoting cancer growth." (PMID 34758182, 2022). "For initial functional studies, we used three IL13Rα2-expressing human cancer cell lines." (PMID 35939683, 2022). "In addition to low affinity receptors, IL-13 also binds to high affinity receptors such as IL13Rα2 in cancer cells." (PMID 35612318, 2022). "Recombinant immunotoxins were the first strategy to target IL-13Rα2 in cancer." (PMID 35464460, 2022). "In other cancer types, the mechanisms and signal transduction of IL-13Rα2 have also been reported." (PMID 34201539, 2021). "However, IL-13Ra2 expression is heterogenous in most cancers and because of the heterogeneity in expression, it is possible one will miss samples by EUS-FNA." (PMID 34201539, 2021). "In addition, IL-13 appears to play its own distinct role in cancer cells through binding to IL-13Rα2 with high affinity and mediating invasion and metastasis via IL-13Rα2, ERK/activator protein 1 (AP-1) signaling, and matrix metalloproteinases (MMPs) pathways." (PMID 33804263, 2021). "A recent study revealed that IL13Rα2 might be an important therapeutic target in a perineural invasion, the invasion of cancer to nerves." (PMID 33917914, 2021). "In another study, IL13Rα2 was closely related to cancer cell migration, which indicated that IL13Rα2 might be a key factor in metastasis in cancers." (PMID 33917914, 2021). "These positive results predict a potential application to other IL13Rα2 positive cancers." (PMID 33917458, 2021). "The overexpression of IL-13Rα2, particularly in certain types of cancers, has led to the hypothesis that it may serve as a signature gene and a target for cancer detection and therapy." (PMID 34201539, 2021). "Similarly, IL-13Rα2-positive cancer samples showed 75% (117/156) Ne, but IL-13Rα2-negative cancer showed only 54% (54/80)." (PMID 32443847, 2020). "IL-13Rα2 is uniquely expressed in cancer cells, diseased fibroblasts, and macrophages." (PMID 32443847, 2020). "PTP1B silencing or treatment with Claramine, a PTP1B inhibitor, caused a significant decrease in IL-13-mediated adhesion, migration and invasion of IL13Rα2-expressing cancer cells by inhibiting the dephosphorylation of Src Tyr530 and consequently, the phosphorylation of Src Tyr419, AKT and ERK1/2." (PMID 32098194, 2020). "These expression profiles suggested that IL13Rα2 is a novel cancer-testis antigen." (PMID 30718742, 2019).
cancer (continued). "We have previously demonstrated that IL-13Rα2 is an excellent target for various immunotherapy approaches such as IL-13 immunotoxin, IL-13Rα2 cDNA vaccine and combination of both which mediates significant efficacy and increased overall survival in animal models of human cancer." (PMID 30572904, 2018). "Another approach is to insert the natural ligand of special receptor that is enriched in cancer cells to the surface of the virus, for example interleukin-13 receptor α2 chain (IL-13Rα2) and N-terminal fragment of urokinase-type plasminogen activator are in enriched in some kind of cancer cells." (PMID 30799657, 2018). "Since AP-1 is critical in signaling through IL-13Rα2, we believe that in addition to targeting IL-13Rα2, targeting of AP-1 may be an additional approach to immunotherapy of cancer where IL-13Rα2 and AP-1 play a critical role." (PMID 30572904, 2018). "In other cancer types, where IL13Rα2 has been described as a poor prognosis biomarker, FAM120A could also play an important role as regulator of IL13-triggered signaling." (PMID 26682245, 2015). "Positive immunostaining for IL13Rα2 was mainly observed in the membrane of cancer cells." (PMID 26418721, 2015). "Thus, our data suggest that targeting of IL13Rα2 overexpressing cancer stem cells is highly feasible via utilization of scFv47-targeted therapeutic agents such as scFv47-engineered adenovirus." (PMID 26656559, 2015). "With this knowledge of IL-13Rα2 upregulation in the tumors, we hypothesized that our mouse model could be used to study targeted therapy against this cancer marker." (PMID 23421960, 2013). "Since IL-13Rα2 binds to IL-13 with high affinity and then undergoes internalization, expression of this receptor can thereby be targeted for delivery of a bacterial toxin into a cancer cell." (PMID 23421960, 2013). "The reason for the differential histone acetylation and methylation is not known but appears to correlate with IL-13Rα2 expression and may be responsible for variability of IL-13Rα2 expression in cancer cells." (PMID 21477288, 2011). "Since cancer is a heterogeneous disease, drug-induced upregulation of IL-13Rα2 could be used in cancers expressing even low levels of IL-13 α2 to enhance the intensity of the immunotoxin anti-cancer response." (PMID 21477288, 2011). "Thus our results show an enhancement of efficacy of IL-13Rα2 DNA vaccine with ECDα2 protein boost and offers an exciting approach in the development of new DNA vaccine targeting IL-13Rα2 for cancer immunotherapy." (PMID 21067607, 2010). "It is possible that the inhibitory effects of IL-13Rα2 DNA boosted with ECDα2 protein vaccination on Tregs expansion will play a potentially important role in clinical efficacy during the treatment of immunocompromised patients, such as those with cancer." (PMID 21067607, 2010). "In addition, we recently demonstrated that IL-13Rα2 is directly involved in cancer invasion and metastasis in human pancreatic cancer models." (PMID 21067607, 2010). "Therefore, it is suggested that IL-13Rα2 might be important in the metastatic potential of cancer cells, and advanced cancer with higher expression of IL-13Rα2 might benefit from new therapies based on blocking the IL-13Rα2 pathway." (PMID 39598436, 2024). "Therefore, it has been suggested that IL-13Rα2 could serve as a potential therapeutic target for malignant tumors." (PMID 39598436, 2024). "Therefore, IL-13Rα2 has gathered a lot of interest as a possible drug target for treating cancer." (PMID 36830725, 2023). "However, LNCaP cancer cells, which normally express very low levels of IL-13Rα2, showed increased expression of IL-13Rα2 mRNA and protein and increased cell surface expression of IL-13Rα2 following treatment with TSA or 5-aza-dC." (PMID 36830725, 2023). "Additionally, the expression of CHI3L1 and IL‐13Rα2 was elevated in many cancers." (PMID 34758182, 2022). "IL-13Rα2 may also contribute to imaging for cancer detection." (PMID 34201539, 2021).
cancer (continued). "Therefore, PTP1B silencing reduces IL13Rα2 internalization and degradation in cancer cells." (PMID 32098194, 2020). "Nevertheless, down-regulation of IL-13Rα2 or targeting IL-13Rα2 by receptor targeted immunotherapeutic agents, such as IL-13-PE, IL-13Rα2 cancer vaccines or adoptive transfer of chimeric antigen receptor modified T cells targeting IL-13Rα2, may improve the prognosis of patients with PDAC." (PMID 32443847, 2020). "Notably, our data show that CD44 also interacts with IL-13Rα2, which may account for the function of IL-13Rα2 in cancer metastasis." (PMID 30165890, 2018). "Treatment with IL-13-PE at an early time point in cancer development may have selectively hindered the growth and establishment of high IL-13Rα2 expressing cancer cells in the mice, resulting in the formation of tumors with decreased overall expression of this receptor." (PMID 23421960, 2013). "Although the significance of expression of IL-13Rα2 in cancer is not completely clear, our previous studies indicate that IL-13Rα2 could be linked to oncogenesis and metastasis and may provide a potential target for immunotherapy." (PMID 21067607, 2010). "A deeper characterization of the PTP1B molecular networks should contribute to elucidating the molecular connections between IL-13, IL13Rα2, PTP1B, and other mediators in inflammation and cancer progression." (PMID 37963919, 2023). "Albumin can also be functionalized using targeting ligands to specifically address the overexpressed receptors on the surface of cancer cells, i.e., EGFR, folate receptors (FR) or interleukin-13 alpha 2 receptor (IL13Rα2)." (PMID 36234629, 2022). "Multiple promising strategies, including immunotoxins, cancer vaccines, and chimeric antigen receptor (CAR) T cells, have been developed to target IL-13Rα2." (PMID 35464460, 2022). "IL13Rα2 was described to be upregulated following activation of EGFR and mutant EGFRvIII in cancer cells." (PMID 33917458, 2021). "In the case of IL13Rα2, Src activation promotes proliferation, migration and invasion, whereas EGFR activation mainly promotes cancer cell proliferation." (PMID 33917458, 2021). "Therefore, IL13Rα2 could be a potential biomarker to diagnose various cancers." (PMID 33917914, 2021). "In CRC cells, the binding of IL-13 to IL13Rα2 triggers STAT6-independent cellular pathways, promoting migration, invasion and survival of cancer cells through the scaffold protein FAM120A, which participates in the activation of FAK and the PI3K pathway." (PMID 32098194, 2020). "After the treatment with IL-13, cancer cells knocked down for PTP1B, showed an increase of IL13Rα2 on the cell surface together with less protein degradation." (PMID 32098194, 2020). "Remarkably, D1 not only blocked IL-13 binding to IL13Rα2, but also inhibited IL13Rα1-mediated STAT6 activation in both cancer types." (PMID 30318506, 2018). "When cancer cells were incubated with the recombinant CHI3L1 protein (rCHI3L1), the CHI3L1 protein bound IL-13Rα2, indicating an interaction between the two proteins." (PMID 28143526, 2017). "The most up-regulated genes in U87 cells were interleukins and receptors (IL1A, IL13RA2, IL1RN), CT45A5 from the cancer/testis (CT) family of antigens, and the cytoplasmic transporter ATP6V0D2." (PMID 25481245, 2014). "IL13RA2, one of the components of the type I IL13R, is frequently expressed on the surface of different cancer cells." (PMID 18560533, 2008). "These IL‐13Rα2‐CAR‐T cells can recognise and specifically kill only IL‐13Rα2‐positive and not IL‐13Rαl‐positive target cells in vitro via perforin/granzyme B pathway and in vivo animal models of human cancers." (PMID 38685487, 2024). "In contrast, non-malignant MCF-10A and non-TNBC MCF-7 cancer cells did not exhibit detectable IL-13Rα2 protein expression." (PMID 37345109, 2023).
cancer (continued). "IL-13 effects on cancer inflammation and invasion have not been thoroughly investigated, despite IL-13 drives the expression of IL13Rα2, a promising therapeutic target for GBM and other tumors." (PMID 37963919, 2023). "Furthermore, given the potentially altered growth characteristics of cancer cells in spheroids, we further tested the ability of HDAC or DNMT inhibitors to modulate IL-13Rα2 expression." (PMID 37345109, 2023). "Finally, to explore the clinical relevance of SHN3, we investigated the prognostic value of SHN3, together with IL13Rα2, PTP1B and MMP9 in GBM and other cancers using the Betastasis (REMBRANDT), PRECOG and the Human Protein Atlas (HPA) databases." (PMID 37963919, 2023). "Since the IL-13Rα2 protein functions mainly at the cell surface, we have also assessed its cell surface expression in the prostate non-cancer and cancer cell lines via cell surface ELISA." (PMID 36830725, 2023). "The addition of both E12K and R109K mutations into an IL13-based CAR also showed attenuated, but not abolished, recognition of IL13Rα1-expressing cancer cells relative to IL13Rα2-expressing cancer cells." (PMID 35939683, 2022). "Thus, our data indicated that K284 blocks the formation of the CHI3L1/IL‐13Rα2 complex and the downstream signaling of JNK, AKT, and AP‐1 pathways leading to the inhibition of cancer cell growth." (PMID 34758182, 2022). "This study provides evidence for the first time that PTP1B mediates IL13Rα2 pro-tumorigenic activities in the three types of cancer and may provide a novel therapeutic target to inhibit IL13/IL13Rα2 signaling." (PMID 32098194, 2020). "Therefore, IL-13/IL-13Rα2 use the PI3K/AKT/mTOR and MAP kinases signaling that, in turn, induces the activation of the AP-1 complex to promote human cancer metastasis." (PMID 32098194, 2020). "Our present observations for the expression of IL-13Rα2 in PNI suggest that IL-13Rα2 may have an important and novel role in pain, not only in PDAC but other PNI mediated cancers." (PMID 32443847, 2020). "The expression of IL-13Rα2, a unique receptor that binds IL-13 with high affinity and involved in signaling in cancer cells, is over expressed in cancer while its expression is mostly absent or low on other tissues except expression in testicular tissue." (PMID 23421960, 2013). "TSA treatment enhanced the cytotoxicity of IL-13-PE in IL-13Rα2-negative cancer cells (IC50 40-50 ng/ml with 5 μM TSA), but not in normal cells (IC50 > 1000 ng/ml with 5 μM TSA)." (PMID 21477288, 2011). "The significance of IL-13Rα2 expression in cancer is not known and the mechanism of its upregulation is still not clear." (PMID 21477288, 2011). "IL-13-PE inhibited protein synthesis in IL-13Rα2-positive cancer cells (IC50 between 10 and 50 ng/ml) without TSA, but not in IL-13Rα2-negative cancer cells nor normal cells (IC50 > 1000 ng/ml)." (PMID 21477288, 2011). "Successful translation of an IL13Rα2 ADC for DIPG would provide a promising new therapeutic to a pediatric disease which lacks any viable life-saving treatment options and would enable broader clinical use of an immunoconjugate agent for a cell surface target overexpressed in numerous cancer types." (PMID 34001278, 2021). "Indeed, the IL-13/IL13Rα2 signaling axis activates Src through PTP1B and then activates the Ras → Raf → MAPK cascade followed by the AP-1 transcriptional pathway in a number of human cancers." (PMID 33917458, 2021). "However, the mechanism of overexpression of IL-13Rα2 and its role in human cancer is not clear and under investigation." (PMID 32443847, 2020). "IL13Rα2 expression is specific for cancer cells while IL13Rα1 is not." (PMID 30318506, 2018). "Because of the selective expression of IL-13Rα2 in several types of tumors but not in normal tissues, we hypothesized that IL-13Rα2 may be a potential target for a cancer vaccine." (PMID 21067607, 2010).